WDR5 (WD repeat domain 5)
Diseases named in the same sentence as WDR5 in open-access papers (continued):
Sharing a sentence is not in itself a finding about the gene and the disease.
tumor (65 papers, 2015 to 2026). "That is why overall tumor inhibitive effects mediated by WDR5 inhibitor or degrader were different with those mediated by WDR5 deficiency only in CD45- tumor cells in the tumor microenvironment." (PMID 39201460, 2024). "An analysis of H3K4me3 showed that the ablation of Wdr5 caused attenuated H3K4me3 expression in total tumor tissues." (PMID 39201460, 2024). "PTENα/β, two variants of PTEN, play a key role in promoting tumor growth by interacting with WDR5 through their N-terminal extensions (NTEs)." (PMID 38744853, 2024). "WDR5, a crucial member of the MLL/SET1 complexes with methyltransferase activity, has been reported to be markedly upregulated in BLCA, and the overexpression of WDR5 was associated with advanced tumor stage and shorter survival." (PMID 35125116, 2022). "Previously, we proposed a tumor-promoting role of PTENα/β, which was dependent on its association with WDR5 in the nucleus." (PMID 35668069, 2022). "Though WDR5 expression level was significantly associated with clinical outcome, such an association vanished when analyzing ER positive tumours alone in BreastMark." (PMID 26355959, 2015). "Our observations in MCF7 confirm previous studies at the transcriptional level and recapitulate our findings in the survival analysis, implying an association between low WDR5 expression and good prognosis via reduced tumour cell viability." (PMID 26355959, 2015). "Consequently, CD8+/CD4+ T-cell infiltration was significantly enhanced and neutralized the tumor-promoting effect mediated by Wdr5 deficiency-induced MHC I downregulation." (PMID 39201460, 2024). "Collectively, these data show that WDR5 is overexpressed in BCa tumour tissues, and associated with advanced and malignant features, indicating that WDR5 may serve as a marker of poor prognosis in BCa." (PMID 34154613, 2021). "However, Wdr5 deficiency in tumor cells has minimal effects on tumor cell growth in vitro." (PMID 39201460, 2024). "Therefore, although the underlying mechanism should be analysed, the tumour promoting role of ALKBH4 in NSCLC might partly rely on WDR5." (PMID 33883577, 2021). "Protein profiling identified ITH-associated proteins (WDR5, CKB, IPO11, ATP6V1F, DCXR and PCCB) and underscored pathway variations including tumour suppressor and proto-oncogenic signalling, vascularization and metabolic regulation." (PMID 41580526, 2026). "ASO-mediated knockdown of MIR31HG reduced tumor stemness and metastasis by recruiting the WDR5/MLL3/P300 complex to modulate the expression of GLI2." (PMID 41409273, 2025). "Nevertheless, CD8+ and CD4+ cells’ tumor infiltration was enhanced dramatically after the depletion of Wdr5, which is consistent with elevated CD8/CD4 expression in RNA level." (PMID 39201460, 2024). "To determine the human relevance of this study, we first analyzed the TCGA database for WDR5 expression in the RNA level of different human tumor types." (PMID 39201460, 2024). "On the other hand, the WDR5/MLL1-H3K4me3 axis regulates the expression of cytokines in the tumor microenvironment, such as TGFβ, TNFα1, and IL6." (PMID 39201460, 2024). "The results revealed that ectopic expression of wild-type WDR5 promoted potent cell proliferation and tumor growth in comparison to all other cell lines." (PMID 38744853, 2024). "Our analysis of the impact of WINi on the WDR5 interactome, for example, identified more than a dozen novel proteins that are displaced from WDR5 by WINi, including tumor-relevant factors such as PDPK1 and mTORC2." (PMID 38202281, 2024). "Previous studies have shown that WDR5 plays an important role in promoting tumor progression and chemoresistance." (PMID 39350229, 2024). "The depletion of Wdr5 dramatically suppressed MHC I (H2Kb/H2Db) expression in the RNA level in the total tumor tissues." (PMID 39201460, 2024).
tumor (continued). "Our data determine that WDR5 not only regulates tumor cell immunogenicity to suppress tumor growth but also activates immune suppressive pathways to promote tumor immune evasion." (PMID 39201460, 2024). "In conclusion, our study has revealed a novel binding motif within PTENα/β-NTE interacting with the WIN site of WDR5 to control downstream histone methylation and increase tumorigenic genes expression, cell proliferation, and tumor growth." (PMID 38744853, 2024). "Among the pure bottleneck proteins, beta-COP, cAspAT, Gal-3, lactotransferrin, PDHE1-B, N-WASP, and WDR5 resulted in significantly varied tumor samples based on statistical comparisons." (PMID 39195201, 2024). "For example, specific inhibition of the WDR5–MYC interaction has shown a reduction in tumor malignancy, as the function of the MYC transcription factor relies on WDR5 for gene recognition." (PMID 37568727, 2023). "Selective PROTAC degraders targeting WDR5 have been reported and demonstrated to effectively suppress tumor growth in vivo and improve survival rates in an AML-PDX xenograft model." (PMID 37568727, 2023). "Further in vitro and in vivo experiments suggested that WDR5 promoted tumor growth and enhanced the chemoresistance of tumor cells to cisplatin." (PMID 35125116, 2022). "Consistent with this idea, knockdown of WDR5 independently decreases primary tumor growth and lung metastasis in vivo." (PMID 36043466, 2022). "In TCGA molecular subtypes, WDR5 expression was the lowest in luminal infiltrated tumour tissues, but gradually increased as malignancy progressed from luminal papillary, luminal, basal squamous, to neuronal tumour tissues." (PMID 34154613, 2021). "WDR5 knockdown showed a significantly slower tumor growth and smaller tumor weight than control group, and these phenomena were more prominently in cisplatin treatment compared with PBS." (PMID 33754029, 2021). "Collectively, these data strongly indicated that targeting WDR5 not only suppressed tumour proliferation and enhance the efficacy of cisplatin for BCa cells in vivo but also reduced the toxicity and side effects for normal tissues." (PMID 34154613, 2021). "When the exon swap system was assessed in vivo, switching to the WDR5-interaction-defective Myc resulted in apoptosis, decreased tumor volume, and improved survival." (PMID 33322239, 2020). "Similar to H3K27ac and H3K4me3 signal, EP300 and WDR5 were also significantly enriched in circSOD2 promoter from HCC tumor tissues compared to normal liver tissues." (PMID 33234142, 2020). "Conversely, WDR5 overexpression increased tumor growth in MCF10DCIS cells, paralleling scattered evidences of correlation of WDR5 overexpression with tumorigenesis." (PMID 31752957, 2019). "A large body of evidence supports the pivotal role of WDR5 in tumor growth and proliferation, differentiation, and metastasis, and suggests that its expression is prognostic in different tumor types." (PMID 31752957, 2019). "The reduction of WDR5 expression significantly inhibited tumor growth in MBC PDXs and in TN and LB cell lines, suggesting that WDR5 is involved in tumorigenesis both in ER+ and ER− BC." (PMID 31752957, 2019). "Accordingly, WDR5 silencing significantly reduced in vitro cell proliferation, as demonstrated in other tumor types." (PMID 31752957, 2019). "WDR5 silencing strongly reduced tumor volume in vivo (P < 0.001), confirming its crucial role in sustaining BC growth." (PMID 31752957, 2019). "Disrupting WDR5 through inhibition assays led to arrested tumor progression and increased survival in PDX mouse models of PDAC117." (PMID 30190481, 2018).
tumor (continued). "Given that EMT is a critical event involved in tumor invasion–metastasis cascade, the impact of WDR5 on EMT was analyzed based on the expression levels of EMT-specific proteins." (PMID 28300833, 2017). "In contrast, overexpression of WDR5 obviously accelerated the tumor growth in vivo compared with the PCDH-vector group." (PMID 25656485, 2015). "In our next step, we will explore the prognostic value of WDR5 in ER positive tumours using more datasets encompassing sufficient tumour samples." (PMID 26355959, 2015). "Additionally, our studies suggest that the combined use of inhibitors targeting both the WIN site and the WBM site of WDR5 would be more effective in suppressing tumor growth than using the individual site inhibitor, which aligns with a recent research." (PMID 38744853, 2024). "Interactions of WDR5 with other proteins such as MYC may also play a role in promoting tumor growth." (PMID 38744853, 2024). "XRCC1 and WDR5 were not present in healthy control tissues, suggesting their specific tumor-associated roles." (PMID 39195201, 2024). "In addition, in the subcutaneous xenograft model, WDR5 knockdown inhibited tumor growth and decreased the Ki-67 expression rate compared with that in the control group, whereas WDR5 overexpression had the opposite effects." (PMID 39350229, 2024). "Compared with normal tissues, whether ABCG2, TOX3, or WDR5 is up-regulated in clinical metastatic and drug-resistant tumor specimens, and shows a strong prognostic value for OS and DFS in drug-resistant CRC patients." (PMID 37708089, 2023). "Moreover, previous study demonstrated that WDR5 served as a tumor-promoter in NB and high level of WDR5 was positively correlated with poor prognosis of NB patients." (PMID 37741985, 2023). "Thus, a new therapeutic strategy that can achieve complete and sustained blockage all of WDR5’s multifaceted oncogenic functions in tumor is desirable." (PMID 34586829, 2021). "Thus, we determined to investigate the clinical significance and the tumor-promoting mechanisms of WDR5 in PCa in this study." (PMID 33754029, 2021). "WDR5 was markedly overexpressed in tumour tissues compared with normal adjacent tissues." (PMID 34154613, 2021). "Interestingly, parallel evolutionary patterns were exhibited in the phylogenetic trees, including mutations in MLLT10, WDR5, and ERMARD, which indicated the diversity of tumor genome evolution." (PMID 33078899, 2020). "More evidence points to the tumor-promoting activity of WDR5." (PMID 33302406, 2020). "OICR-9429 significantly reduced BC cell line migration in a dose-dependent manner, while it did not affect the migration of the MCF10A non-transformed cells, suggesting that WDR5 inhibition may exert specific effects on tumor cells." (PMID 31752957, 2019). "Furthermore, gene expression microarrays were used to identify ZNF407, which was reported to affect tumor progression, as a novel target of WDR5, which markedly increased CRC cell migration." (PMID 28300833, 2017). "As EMT stays crucial in tumor migration and invasion during progression and the acquisition of stemness properties, we tested whether WDR5 affected cell motility by inducing EMT." (PMID 28300833, 2017). "Given the large sample size and comprehensive information on subtype classification in BreastMark, we also conducted the DFS analysis in luminal A and luminal B tumours (both are ER positive) as the MLL2 complex (comprising WDR5) is known to critically affect ER signalling." (PMID 26355959, 2015). "Interestingly, the growth of tumors derived from the WDR5 knockdown group was prominently suppressed compared with the control group from 2 weeks after tumor inoculation." (PMID 25656485, 2015). "The WDR5 protein level was correlated with the Ki67 protein level in the animal tumor tissues." (PMID 25656485, 2015). "Furthermore, WDR5 knockdown decreased the expression of Nanog, whereas overexpression of WDR5 increased the expression of Nanog in the animal tumor tissues." (PMID 25656485, 2015).
tumor (continued). "Furthermore, WDR5 promoted bladder cell proliferation, self-renewal and chemoresistance to cisplatin in vitro, and accelerated tumor growth in vivo." (PMID 25656485, 2015). "Biologically, WDR5 may contribute to tumor sphere formation and cell proliferation." (PMID 36043466, 2022). "In addition to metastatic colonization from circulation, we tested whether knockdown of WDR5 affects tumor growth and metastasis from the orthotopic mammary fat pad." (PMID 36043466, 2022). "In addition, reverse transcription polymerase chain reaction (RT-PCR) analysis of these tumor samples revealed that the MS67 treatment led to down-regulation of WDR5 target genes such as ribosome subunits and oncogenesis-related transcripts including BCL2 and CSNK1E." (PMID 34586829, 2021). "Histone lysine methyltransferase 2D (KMT2D) enhances the stability of the WDR5 protein via LLPS, facilitates the formation of the KMT2D‐enzyme complex, and catalyses the monomethylation of H3K4 to stimulate tumour growth." (PMID 40211955, 2025). "An alternative strategy is targeting WDR5, crucial for GSC self-renewal and tumor initiation, by disrupting the epigenetic maintenance of GSCs and circumventing the challenges of directly targeting transcription factors like SOX2." (PMID 40565099, 2025). "Enhance the stability of the WDR5 protein, promote the synthesis of the KMT2D‐enzyme complex and stimulate tumour growth." (PMID 40211955, 2025). "First, using subcutaneous tumor formation in mice, we observed that NSUN5 overexpression increased HCC proliferation, an effect significantly attenuated by reducing WDR5 levels in HepG2‐ov‐NSUN5 cells." (PMID 39531371, 2025). "HBx activates multiple tumor‐related genes, including ALKBH5 and MMP, through WDR5‐driven modification." (PMID 40060195, 2025). "As expected, WDR5-47 decreased the H3K4me3 level dose dependently in PANC02 cells and inhibited the tumor cell viability both dose dependently and time dependently." (PMID 39201460, 2024). "To further demonstrate the regulatory function of Wdr5 on MHC I molecules in vivo, we analyzed the MHC I expression in total tumor tissues." (PMID 39201460, 2024). "To validate the regulation of MHC I by Wdr5 in protein levels, we analyzed H2Kb/H2Db expression in CD45− cells from total PANC02 tumor tissues by flow cytometry." (PMID 39201460, 2024). "While in PDAC, WD repeat domain 5 (WDR5), a histone methyltransferase, mediates H3K4me3 on promoters of OPN and CD44 and enhances their expression to promote PD-L1 expression in tumor cells and MDSCs." (PMID 36906534, 2023). "In tumor samples collected from mice 2 hours after the last dose of MS67 or vehicle for 5 days, we found that WDR5 was substantially degraded in the MS67 treated, compared to the vehicle treated." (PMID 34586829, 2021). "Then, MCF10DCIS cells were transduced with the two pooled WDR5 shRNAs and a corresponding control (shLuc) and transplanted in NOD/SCID mice to assess in vivo tumor growth (n = 9 per group)." (PMID 31752957, 2019). "However, knocking down WDR5 in NSUN5‐overexpressing HCC cells significantly reduced the number and size of metastatic lesions in the lungs, accompanied by decreased metastatic tumor volume in the lungs, as validated via IHC staining." (PMID 39531371, 2025). "Although the function of the WDR5/MLL1-H3K4me3 axis has been extended from hematopoietic cancer to solid tumor, its roles in tumor cells and immune cells, respectively, in solid tumor is still largely unknown." (PMID 39201460, 2024). "Furthermore, in addition to PTENα, WDR5 also interacts with various proteins through its WIN site and these interactions are extensively reported to be involved in tumor progression." (PMID 38744853, 2024). "This may also be due to the removal of WDR5 from both CD45− and CD45+ cells in the tumor microenvironment." (PMID 39201460, 2024). "However, how WDR5-47 coordinates CD45- and CD45+ cells to repress tumor growth in vivo requires further study." (PMID 39201460, 2024).
tumor (continued). "Unexpectedly, the depletion of Wdr5 did not change tumor size and weight dramatically." (PMID 39201460, 2024). "Genetic disruption of the c-MYC–WDR5 interaction in a Burkitt lymphoma cancer context results in impaired tumorigenesis and tumor regression revealing the importance of the MYC–WDR5 interaction to tumor function and implicating WDR5 as an essential MYC interaction partner." (PMID 37336886, 2023). "Furthermore, the mRNA expression of FBXW7 was decreased and that of WDR5 was increased in BDNF-AS-overexpressing tumor tissues, but VDAC3 expression was not significantly changed." (PMID 35280682, 2022). "Furthermore, MS67 induced substantial WDR5 degradation and significant tumour growth inhibition in subcutaneous mouse xenograft models and induced prolonged mouse survival, indicating therapeutic potential of MS67 for treatment of WDR5-dependent tumours." (PMID 35983982, 2022). "In addition, lacking WDR5 expression does not induce tumour cell resistance to doxorubicin, allowing its combined usage with traditional chemotherapy, e.g. anthracycline, once such a regimen is available." (PMID 26355959, 2015). "However, this interaction is not the only requirement for pro-tumor activity of WDR5." (PMID 38744853, 2024). "WDR5 was identified as a key epigenetic regulator in GSC organoids, and pharmacological WDR5 inhibition suppressed several stem cell marker genes and reduced self-renewal and tumor initiation, indicating that epigenetic regulatory scaffolds may provide feasible targets specifically in GSCs." (PMID 37444568, 2023). "Moreover, MS67, but not OICR-9429, effectively degraded WDR5 in these tumor samples." (PMID 34586829, 2021). "The MYC‐WDR5 nexus has been shown to promote induced pluripotent stem cell generation and drive oncogenesis, and WDR5, as a key determinant of MYC recruitment to chromatin, may be an effective target for developing anti‐tumour medicaments against MYC‐driven tumours." (PMID 32394588, 2020). "Knocking down WDR5 in MCF7 dramatically decreases cell viability, but does not alter tumour cell response to doxorubicin." (PMID 26355959, 2015).
infection (6 papers, 2015 to 2025). The state of being infected such as from the introduction of a foreign agent such as serum, vaccine, antigenic substance or organism. "Protein expression of WDR5 and WDR5B was verified by Western blot, although equal multiplicity of infection (MOI) transduction of ARPE-19 cells resulted in ~5-fold higher WDR5-FLAG levels compared to WDR5B-FLAG." (PMID 39056772, 2024). "First, the expression of WDR5 was significantly elevated in NCM460 cells by OE‐WDR5 infection." (PMID 40586619, 2025). "Although one model is generally indicated that Ifng-AS1(NeST) was required for Ifng expression in response to infection with Salmonella, and Ifng-AS1(NeST) was found to bind WDR5 component of histone H3 lysine 4 methytransferase complex, and to modify H3K4me3 at the Ifng locus by CD8+ T cells." (PMID 26634912, 2015).